DANCR (differentiation antagonizing non-protein coding RNA)
Diseases named in the same sentence as DANCR in open-access papers (continued):
Sharing a sentence is not in itself a finding about the gene and the disease.
osteoporosis (14 papers, 2017 to 2025). A condition of reduced bone mass, with decreased cortical thickness and a decrease in the number and size of the trabeculae of cancellous bone (but normal chemical composition), resulting in increased fracture incidence. "Bone disorders such as osteoporosis and bone metastases are linked to DANCR dysregulation." (PMID 39156986, 2024). "However, the cause of DANCR upregulation in osteoporosis patients remains elusive and needs to be further investigated." (PMID 32778797, 2020). "By specifically targeting DANCR, therapeutic potential is shown for the restoration of normal bone metabolism, the modulation of signaling pathways associated with bone, and the development of novel treatments for a variety of bone illnesses, such as osteoporosis and bone malignancies." (PMID 39156986, 2024). "Several lncRNAs, including Malat1, H19, HOTAIR, MEG3 and DANCR, were largely involved in the osteoporosis." (PMID 36983039, 2023). "Bone marrow-derived stem cells (BMSCs) from osteoporosis patients were derived, and researchers observed a relatively high expression of DANCR." (PMID 36553535, 2022). "In the present study, we have identified the lncRNA DANCR a key factor for sesamin-mediated osteogenesis and osteoclastogenesis, as well as the regulator in osteoporosis pathogenesis." (PMID 34960006, 2021). "In summary, our results show that the efficacy of sesamin in osteoporosis is through the regulation of DANCR expression and the downstream Wnt/β-catenin and NF-κB signaling pathways during osteogenesis and osteoclastogenesis, respectively." (PMID 34960006, 2021). "Both IL-6 and TNF-α promote bone resorption, and the positive correlation of DANCR with serum levels of IL-6 and TNF-α in osteoporosis patients suggest the involvement of DANCR in the pathology of osteoporosis." (PMID 32992908, 2020). "Accordingly, we proved in the present study that DANCR overexpression was positively correlated with osteoporosis and efficiently inhibited osteogenic differentiation in BMSCs." (PMID 32778797, 2020). "Taken together, our findings revealed that DANCR and miR-320a regulated the Wnt/β-catenin signaling pathway during osteogenic differentiation in osteoporosis through CTNNB1 inhibition." (PMID 32778797, 2020). "The expression levels of DANCR and miR-320a in BMSCs derived from osteoporosis patients were upregulated, whereas CTNNB1 expression was downregulated compared with that in healthy controls." (PMID 32778797, 2020). "It was previously reported that DANCR was upregulated in blood mononuclear cells from osteoporosis patients and increased bone resorption activity by secreting osteoclastogenic factors such as IL-6 and TNF-α23." (PMID 32778797, 2020). "DANCR expression correlates with low bone mineral density osteoporosis." (PMID 41158629, 2025). "Further evidence demonstrates that blood mononuclear cells with upregulated DANCR expression could lead to osteoporosis, thereby increasing the secretion of IL-6 and TNF-α as well as bone resorbing activity." (PMID 38589566, 2024). "As DANCR is overexpressed in osteoporosis, DANCR can be a target against osteoporosis." (PMID 37675799, 2023). "In previous studies, which indicated that DANCR might influence the pathological process of osteoporosis, researchers assessed the expression of DANCR during osteoblast induction of BMSCs, and results indicated that the expression of DANCR gradually decreased." (PMID 36553535, 2022). "Additionally, it was noticed that in BMSCs derived from osteoporosis patients, DANCR expression was decreased during osteoblast induction." (PMID 36553535, 2022). "have demonstrated that DANCR is overexpressed in monocytes in osteoporosis." (PMID 32791451, 2020). "Inhibition of DANCR expression, for example using antisense molecules blocking the DANCR expression, may yield satisfactory results in osteoporosis, as well as RA therapy." (PMID 32791451, 2020).
osteoporosis (continued). "Overexpression of DANCR increased the secretion of IL-6 and TNF-α in blood mononuclear cells, both of which were inflammatory cytokines and important mediators of accelerated bone loss in osteoporosis." (PMID 29441193, 2018). "Therefore, we hypothesized that the DANCR/hsa-miR-23b-3p/B4GALT4 axis may provide novel molecular insights into the development of osteoporosis." (PMID 38589566, 2024). "Furthermore, the DANCR/hsa-miR-23b-3p/B4GALT4 axis might provide novel molecular insights into the process of osteoporosis development." (PMID 38589566, 2024). "Furthermore, the DANCR/hsa-miR-23b-3p/B4GALT4 axis may provide novel molecular insights into osteoporosis development." (PMID 38589566, 2024). "Although we have elucidated the involvement of DANCR in the regulation mechanism of sesamin on Wnt/β-catenin and NF-κB signaling in in vitro whether these two signaling pathways are predominant in the observed efficacy of sesamin in osteoporosis is yet to be explored in in vivo OVX mouse models." (PMID 34960006, 2021). "Consistent with our in vitro experiments, we reported in the present study that DANCR and miR-320a were overexpressed and CTNNB1 was expressed at low levels in our osteoporosis mouse model, leading to the inhibition of the β-catenin signaling pathway." (PMID 32778797, 2020). "To elucidate the biological functions of DANCR, miR-320a, and CTNNB1 in osteoporosis pathogenesis, we first verified and compared their expression levels in BMSCs derived from osteoporosis patients with those in control cells." (PMID 32778797, 2020). "Overall, we identified for the first time aberrant expression of DANCR, miR-320a, and CTNNB1 in osteoporosis patients and an OVX animal model." (PMID 32778797, 2020). "However, further efforts are needed to investigate whether and how other molecules interact with DANCR, miR-320a, and CTNNB1 during osteoporosis development, and the important question regarding the reason for DANCR upregulation in osteoporosis patients remains unanswered." (PMID 32778797, 2020). "Our findings highlight for the first time the role of the interactions between DANCR, miR-320a, and CTNNB1 in osteogenic differentiation and may aid the development of novel therapies for osteoporosis." (PMID 32778797, 2020). "Furthermore, DANCR promotes RANKL-induced osteoclast formation, which also affects the development of osteoporosis." (PMID 32791451, 2020). "There is evidence that lncRNA-ANCR (anti-differentiation non-coding RNA), also known as DANCR (differentiation antagonizing non-protein coding RNA), promotes osteoporosis." (PMID 32664424, 2020). "Furthermore, we reported for the first time that DANCR expression was positively correlated with the expression of miR-320a during osteoporosis development and that CTNNB1 expression was negatively correlated with the expression of DANCR and miR-320a." (PMID 32778797, 2020). "To validate the involvement of DANCR in osteoporosis, which we observed in the qRT-PCR results, after determining the DANCR overexpression or knockdown transfection efficiency in BMSCs, we found that the expression level of miR-320a was not affected by DANCR overexpression or knockdown." (PMID 32778797, 2020). "When studying NR_024031, also named DANCR, researchers found that DANCR promoted the expression of IL-6 and TNF-α, and DANCR-induced IL-6 and TNF-α had bone-resorbing activity indicating that DANCR is involved in the pathology of osteoporosis and may be a biomarker for postmenopausal osteoporosis." (PMID 28173844, 2017). "However, the role of the interactions between DANCR, CTNNB1 and miR-320a in osteoporosis has not been investigated or reported." (PMID 32778797, 2020).
pancreatic cancer (14 papers, 2020 to 2023). "Upregulated DANCR expression was associated with poor prognosis and short overall survival time in patients with pancreatic cancer." (PMID 34722539, 2021). "Previously, an interaction between IGF2BP2 and DANCR has been implicated in pancreatic cancer, where IGF2BP2 promotes DANCR expression and DANCR contributes to tumorigenesis and cancer cell growth." (PMID 35141227, 2021). "Hence, DANCR was associated with pancreatic cancer development and regarded as a promising target for pancreatic cancer prognosis and treatment." (PMID 34722539, 2021). "In pancreatic cancer cells, DANCR regulates expression of miR-33b to promote proliferation and metastatic abilities." (PMID 35590326, 2022). "For instance, IGF2BP2 enhances DANCR stability, functioning as an m6A reader for m6A-modified DANCR mRNA in the maintenance of pancreatic cancer stemness." (PMID 36438499, 2022). "Knockdown of DANCR suppressed pancreatic cancer cell proliferation, migration, invasion in vitro, and tumor growth in vivo." (PMID 34722539, 2021). "DANCR was downregulated by miR-135a through regulating of downstream protein NLRP3 in pancreatic cancer." (PMID 33123287, 2020). "The lncRNA DANCR functions as an oncogene in various cancers, but elucidation of its role in pancreatic cancer (PC) requires further investigation." (PMID 31515968, 2020). "Taken together, these results suggest that DANCR promotes stemness-like properties of pancreatic cancer cells." (PMID 31804607, 2020). "The present study suggests that m6A-mediated upregulation of DANCR promotes stemness like properties in pancreatic cancer." (PMID 31804607, 2020). "Further characterization revealed that DANCR promotes the cell proliferation, stemness-like properties as well as tumorigenesis of pancreatic cancer cells." (PMID 31804607, 2020). "To determine the effect of DANCR on pancreatic cancer tumorigenesis, we tested three different numbers of cancer cells (1 × 104 cells/mouse; 1 × 105 cells/mouse and 5 × 105 cells/mouse)." (PMID 31804607, 2020). "Additionally, DANCR plays a key role in pancreatic cancer via modulating tumor cell proliferation and immune response." (PMID 37540295, 2023). "DANCR showed higher expression in pancreatic cancer cell lines and tissues." (PMID 34722539, 2021). "In addition, DANCR sponged several miRNAs to regulate the expression of target mRNAs in pancreatic cancer cells." (PMID 34722539, 2021). "To determine whether DANCR is involved in the IGF2PB2-mediated pancreatic cancer progression and stemness-like properties, we ectopically expressed DANCR in BXPC-3 and SW1990 cells." (PMID 31804607, 2020). "For instance, in pancreatic cancer, IGF2BP2 acts as an m6A reader to regulate the expression of DANCR, thus promoting the proliferation and invasion of pancreatic cancer cells." (PMID 36871072, 2023). "The lncRNA DANCR and IGF2BP2 (reader) have been proven to synergistically promote the pathogenesis of pancreatic cancer." (PMID 34238292, 2021). "Together, these results suggest that DANCR is a novel target for IGF2BP2 through m6A modification, and IGF2BP2 and DANCR work together to promote cancer stemness-like properties and pancreatic cancer pathogenesis." (PMID 31804607, 2020). "Here, we provide evidence that DANCR is a novel m6A modified target that can be recognized by IGF2BP2, leading to an increased stability of DANCR in pancreatic cancer." (PMID 31804607, 2020). "Recently, DANCR was identified as a novel target of IMP2 through m6A modification, and IMP2 and DANCR exert their functions jointly to promote cancer stemness-like properties and pancreatic cancer pathogenesis." (PMID 34743750, 2021). "Similarly, in pancreatic cancer cells, the m6A reader IMP2 shows remarkably enhanced expression and translation of lncRNA and DANCR by targeting its m6A-containing motif, which mutually accelerates the initiation and progression of pancreatic cancer." (PMID 34743750, 2021).
pancreatic cancer (continued). "And DANCR could promote pancreatic cancer cell growth and metastasis through working as a competing endogenous RNA (ceRNA) of miR-214-5p, and positively regulate E2F2 expression in pancreatic cancer cells." (PMID 33123287, 2020). "However, little is known about the function of DANCR in pancreatic cancer, and in particular, it is not known whether DANCR is subject to m6A modification." (PMID 31804607, 2020).
bladder cancer (13 papers, 2018 to 2026). "Cumulatively, our results suggest that DANCR is a powerful tumor biomarker, which highlight its potential clinical utility as a promising diagnostic and therapeutic target of bladder cancer." (PMID 30419948, 2018). "Together, our results suggest that DANCR is a powerful tumor biomarker, which highlight its potential clinical utility as a promising diagnostic and therapeutic target of bladder cancer." (PMID 30419948, 2018). "This study is the first to demonstrate that DANCR plays a critical regulatory role in bladder cancer cell and DANCR may serve as a potential diagnostic biomarker and therapeutic target of bladder cancer." (PMID 30419948, 2018). "DANCR is located at 4q12.5, which is one of the most critical regulatory RNAs in diverse tumors, such as bladder cancer, nasopharyngeal carcinoma, liver cancer, and esophageal cancer." (PMID 41602364, 2026). "Through activating IL11-STAT3 signaling and CCND1, DANCR promoted the metastasis and proliferation of bladder cancer cells." (PMID 41602364, 2026). "In this way, DANCR overexpression in bladder cancer leads to a pathological activation of pro-lymphangiogenic VEGF-C signaling, thereby promoting tumor lymphangiogenesis and LN metastasis." (PMID 37407839, 2023). "In bladder cancer cells, DANCR silencing has inhibited proliferation, migratory potential and invasion." (PMID 35590326, 2022). "The relative expression level of DANCR was determined by qRT-PCR in bladder cancer tissues and cell lines." (PMID 30419948, 2018). "DANCR expression was up-regulated in 66.05% (70/106) of bladder cancer tissues compared with the corresponding normal tissue samples." (PMID 30419948, 2018). "The relative expression level of DANCR was determined by Real-Time qPCR in a total of 106 patients with urothelial bladder cancer and in different bladder cancer cell lines." (PMID 30419948, 2018). "Mechanistically, we found that DANCR expression was statistically positively correlated with MSI2 expression in bladder cancer and knockdown of DANCR decreased MSI2 expression in bladder cancer cells." (PMID 30419948, 2018). "Knockdown of DANCR increased E-cadherin expression and decreased N-cadherin and vimentin expression in bladder cancer cells." (PMID 30419948, 2018). "We found that DANCR was significantly up-regulated in bladder cancer cells and DANCR functioned as a miRNA sponge to positively regulate MSI2 expression through sponging miR-149." (PMID 30419948, 2018). "Meanwhile, the expression level of DANCR was significantly up-regulated in bladder cancer cell lines compared with normal urothelial cell line." (PMID 30419948, 2018). "Loss-of-function experiments were performed to investigate the biological roles of DANCR on bladder cancer cell proliferation, migration, invasion and tumorigenicity." (PMID 30419948, 2018). "In addition to EMT, another study reported that DANCR significantly promotes the proliferation, invasion, migration, and lymphatic metastasis of bladder cancer cells by targeting miR-335, upregulating the expression of VEGF-C, a target of miR-335." (PMID 36605618, 2023). "Moreover, MSI2 overexpression significantly reversed cell migration and invasion inhibition of bladder cancer cells induced by silencing DANCR." (PMID 30419948, 2018). "RNA-FISH results revealed that DANCR was distributed mostly in the cytoplasm, suggesting that DANCR might also play a role in posttranscriptional level in bladder cancer." (PMID 30419948, 2018). "Moreover, knockdown of miR-149 reversed the inhibition of MSI2 expression and MSI2 overexpression reversed the malignant phenotype inhibition of bladder cancer cells induced by silencing DANCR." (PMID 30419948, 2018). "Moreover, knockdown of miR-149 reversed MSI2 expression and MSI2 overexpression reversed the malignant phenotype inhibition of bladder cancer cells induced by silencing DANCR." (PMID 30419948, 2018).
bladder cancer (continued). "We found knockdown of DANCR inhibited the tumorigenicity of bladder cancer cells in vivo." (PMID 30419948, 2018). "In this study, we found that DANCR was significantly up-regulated in bladder cancer." (PMID 30419948, 2018). "Then we found knockdown of DANCR increased miR-149 expression in bladder cancer cells." (PMID 30419948, 2018). "We further determined whether DANCR regulated malignant phenotypes of bladder cancer cells via MSI2-dependent manner." (PMID 30419948, 2018). "In addition, DANCR was known to promote progressions of bladder cancer cells by regulating the miR-149/MSI2 axis as a ceRNA, suggesting DANCR could be a therapeutic target against colon cancer." (PMID 32766131, 2020). "We further determined whether DANCR regulated EMT of bladder cancer cells." (PMID 30419948, 2018). "We further determined whether DANCR regulated cell proliferation of bladder cancer cells." (PMID 30419948, 2018). "We further determined whether DANCR regulated cell migration and invasion of bladder cancer cells." (PMID 30419948, 2018). "However, the clinical significance and biological function of DANCR in bladder cancer are completely unknown." (PMID 30419948, 2018). "Our study reveals that DANCR functions as a miRNA sponge to positively regulate MSI2 expression through sponging miR-149 and subsequently promotes the malignant phenotypes of bladder cancer cells, thus playing an oncogenic role in bladder cancer pathogenesis." (PMID 30419948, 2018). "Further experiments demonstrated that knockdown of DANCR inhibited malignant phenotypes (proliferation, migration, invasion and EMT and tumorigenicity) of bladder cancer cells." (PMID 30419948, 2018). "Further experiments demonstrated that knockdown of DANCR inhibited malignant phenotypes and epithelial-mesenchymal transition (EMT) of bladder cancer cells." (PMID 30419948, 2018). "Further experiments demonstrated that knockdown of DANCR inhibited malignant phenotypes (proliferation, migration, invasion, EMT and tumorigenicity) of bladder cancer cells." (PMID 30419948, 2018). "We found knockdown of DANCR decreased MSI2 expression and inhibited EMT of bladder cancer cells in vivo." (PMID 30419948, 2018). "Meanwhile, we found knockdown of DANCR inhibited MSI2 and ki67 expression of bladder cancer cells in vivo." (PMID 30419948, 2018). "Differentiation antagonistic non-protein coding RNA (DANCR), also called ANCR or AGU2, plays an important role in the progression, invasion and metastasis of several cancers, including cervical, pancreatic and bladder cancers." (PMID 37407839, 2023). "In bladder cancer (BC), lncRNA DANCR expression was dramatically higher in BC tissues than in normal controls." (PMID 35150011, 2022). "Recently, Chen and colleagues reported that lncRNA DANCR directly interacted with LRPPRC and guided LRPPRC protein to bind and stabilize the mRNAs of CCND1, PLAU, and IL-11, resulting in enhanced proliferation, migration, and invasion of bladder cancer cells." (PMID 34671012, 2021). "DANCR had been described to competitively bind miR-149 to positively regulate MSI2 expression and promote tumor malignant phenotypes in the pathogenesis of bladder cancer." (PMID 31827393, 2019). "The results showed that DANCR expression levels were statistically positively correlated with MSI2 expression levels in bladder cancer and knockdown of DANCR decreased MSI2 expression in bladder cancer cells." (PMID 30419948, 2018). "Published research manifested that DANCR (differentiation antagonizing non-protein coding RNA) promoted metastasis and proliferation in bladder cancer cells by enhancing IL-11-STAT3 (interleukin-11-signal transducers and activators of transcription-3) signaling and CCND1 expression." (PMID 33931059, 2021).